PTBP3 (polypyrimidine tract binding protein 3)
Diseases named in the same sentence as PTBP3 in open-access papers (continued):
Sharing a sentence is not in itself a finding about the gene and the disease.
tumor (continued). "The results showed that the SLC25A21-AS1 overexpression group significantly inhibited tumor growth, while tumors in the PTBP3 group were larger." (PMID 36717926, 2023). "Motility in the SLC group was, as expected, slower than the control group; addition of PTBP3 restored tumor metastasis to a certain extent, in agreement with the in vitro results." (PMID 36717926, 2023). "Especially in N6-methyladenosine analysis, we found that PTBP3 expression is related to all m6A markers in almost all human tumours, such as DLBC, PRAD, PAAD, LIHC, KIRP, THYM, and UVM." (PMID 35359851, 2022). "To understand the relationship between PTBP3 expression and prognosis and OS, we divided tumour cases into high- and low-expression groups according to the median expression of PTBP3." (PMID 35359851, 2022). "We used the Cancer Genome Atlas (TCGA) to examine the expression levels of PTBP1, PTBP2, and PTBP3 in normal and tumor tissues, and cBioPortal was used to examine the genomic alterations." (PMID 36203873, 2022). "We further investigated the relationship between PTBP3 and clinicopathological characteristics of LUSC and verified that higher PTBP3 expression resulted in larger tumor size than lower PTBP3 expression." (PMID 35016691, 2022). "In 29 of 33 tumours, the expression of PTBP3 was positively correlated with the expression of immune checkpoint CD274." (PMID 35359851, 2022). "We summarized the clinicopathological characteristics of these patients, and the data demonstrated that patients with higher PTBP3 expression showed a larger tumor size than the patients with lower PTBP3 expression." (PMID 35016691, 2022). "Next, we used TIMER2 to explore the expression of PTBP3 in different tumour types in the TCGA repository." (PMID 35359851, 2022). "PTBP3 overexpression also promotes pancreatic ductal adenocarcinoma proliferation in vitro and tumour growth in vivo." (PMID 35359851, 2022). "Next, we summarized the clinicopathological characteristics of the 30 patients in the first cohort, and patients with high PTBP3 expression showed larger tumor sizes than those with low PTBP3 expression." (PMID 35136024, 2022). "A positive relationship between PTBP3 expression and all immune checkpoints was found in the tumours of UVM, STAD, SKCM, OV, LIHC, and LGG." (PMID 35359851, 2022). "We first performed differentiation analysis and correlation analysis on the expression of the PTBP1, PTBP2, and PTBP3 genes in 30 tumor types using TCGA." (PMID 36203873, 2022). "We found strong positive correlations of PTBP1 with Th2 cells, PTBP2 with T helper cells and Tcm, and PTBP3 with T helper cells, Tcm, and Th2 cells in most tumor types." (PMID 36203873, 2022). "Next, we analyzed the correlations between the PTBP3 expression level and clinical features and found that a high PTBP3 expression level was correlated with clinical features, particularly the tumor size." (PMID 35136024, 2022). "In this study, The Cancer Genome Atlas (TCGA) Project and Gene Expression Omnibus (GEO) databases were used to explore the expression profile of PTBP3 across various tumour types." (PMID 35359851, 2022). "Immunohistochemistry (IHC) showed lower Ki67 expression in the PTBP3 knockdown tumor tissue group than in the NC group, suggesting that PTBP3 knockdown suppressed the proliferation of cancer cells." (PMID 35136024, 2022). "This study found a positive correlation between PTBP3 expression and neutrophil cell count in most tumour types, especially in BLCA, CESC, DLBC, KIRC, LIHC, PRAD, and STAD." (PMID 35359851, 2022). "To examine if PTBP3 promotes tumor growth in vivo, we selected nude mice for subcutaneous injection of H520 cells transduced with either sh-NC or sh-PTBP3 lentivirus." (PMID 35016691, 2022). "Comprehensive pan-cancer analysis aims to investigate the potential molecular mechanism of PTBP3 in the pathogenesis, clinical prognosis, and immunotherapy of various human tumours." (PMID 35359851, 2022).
tumor (continued). "The role of PTBP3 in various human tumours was explored and analysed in this study based on the Cancer Genome Atlas and Gene Expression Omnibus datasets." (PMID 35359851, 2022). "PTBP3 can promote colorectal cell proliferation, migration, and invasion in vitro and tumour growth and metastasis in vivo by binding to the 5′UTR HIF-1α mRNA to enhance HIF-1α protein expression." (PMID 35359851, 2022). "After including the GTEx dataset, we further analysed the differences in PTBP3 expression between the tumour and normal tissues." (PMID 35359851, 2022). "Among PTBPs, PTBP1 showed the highest RNA expression level in tumor tissues, followed by PTBP3; the expression level of PTBP2 was the lowest among the three genes." (PMID 36203873, 2022). "It was shown that lncRNA BCRT1 acts as a tumor promoter by competitively binding to miR-1303 and thereby preventing the degradation of the miRNA target gene PTBP3, a tumor promoter in BC." (PMID 33522932, 2021). "The expression of PTBP3 mRNA was found to be significantly higher in PDAC tumour tissue than in matched adjacent non‐tumour tissue." (PMID 31989778, 2020). "In our study, we found that PTBP3 overexpression in NSCLC tissues were correlated with tumor differentiation, lymph node metastasis and distant metastasis status." (PMID 32477006, 2020). "The tumour sections of patients with high levels of PTBP3 also have high levels of ATG12 and LC3‐II." (PMID 31989778, 2020). "PTBP3 overexpression promoted PDAC proliferation in vitro and tumour growth in vivo, whereas PTBP3 depletion had opposing effects." (PMID 31989778, 2020). "Having established that the expression of PTBP3 was higher in PDAC tumour tissue, we next compared mRNA and protein levels of PTBP3 in four different PDAC cell lines (PANC‐1, BxPC‐3, SW1990 and Capan‐2)." (PMID 31989778, 2020). "Further, we analysed the expression of PTBP3 mRNA by using GEPIA confirmed that PTBP3 mRNA expression was higher in PDAC tumour tissue than in non‐tumour tissue." (PMID 31989778, 2020). "Western blotting and immunohistochemical (IHC) analysis confirmed that protein levels of PTBP3 were higher in PDAC tumour tissue than in non‐tumour tissue." (PMID 31989778, 2020). "The expression of Ki‐67 was significantly reduced in xenograft tumours treated with PTBP3 shRNA, whereas PTBP3 overexpression promoted Ki‐67 expression in xenograft tumours." (PMID 31989778, 2020). "In conclusion, these results clearly demonstrated that high PTBP3 expression enhanced tumor growth in vitro and in vivo." (PMID 31291975, 2019). "We also showed that blocking HIF-1α pathway using HIF-1α inhibitor 2-Methoxyestradiol (2-MeOE2) significantly reduced tumor growth formed by PTBP3 overexpression (OE) cell." (PMID 31291975, 2019). "Our data also showed that PTBP3 promoted tumor growth and lung metastasis in an animal model of CRC." (PMID 31291975, 2019). "Given that our results have showed that PTBP3 was an essential factor for tumor growth and metastasis, and angiogenesis is widely believed to play an important role in tumor growth and metastasis." (PMID 31291975, 2019). "Consistent with these previous data, our results showed that PTBP3 KD and OE reduced tumor cell growth, migration, invasion abilities, respectively." (PMID 31291975, 2019). "Previous studies highlighted the oncogenic role of PTBP3 in tumor migration, invasion, growth and metastasis." (PMID 31291975, 2019). "To assess the effect of HIF-1α on PTBP3-mediated tumor growth in vivo, we used 2-MeOE2 to block HIF-1α pathway in the xenografts formed by HCT116 PTBP3 Con/OE cells." (PMID 31291975, 2019). "We have showed that PTBP3 can promote tumor growth, metastasis and angiogenesis, as well as, regulated VEGF expression, which is a direct target of HIF-1A gene." (PMID 31291975, 2019). "Consistent with the in vitro assays, mice with xenografts of PTBP3 KD tumor cells formed smaller tumors both in tumor size and weight in vivo compared with the control group." (PMID 31291975, 2019).
tumor (continued). "By virtue of their characteristics closely mimicking clinical tumor heterogeneity, PDO directly confirmed the enhancing effect of PTBP3 on tumor cell invasion and proliferation, providing highly credible clinically relevant evidence for the oncogenic function of this molecule." (PMID 41583453, 2025). "Increasing evidence has shown that PTBP3 promotes cancer progression in several tumor types." (PMID 38405614, 2024). "In addition, in a mouse xenograft tumor model, knockout of PTBP3 inhibits tumor lymphangiogenesis and metastasis to regional LNs." (PMID 37803421, 2023). "PTBP3 were predicted to be a direct target of miR-297 by all of the four databases and the expression of PTBP3 showed higher expression in tumor tissues compared with their matched adjacent normal tissues in liver hepatocellular carcinoma according to TCGA database." (PMID 37633911, 2023). "This study is the first to report a comprehensive pan-cancer analysis of PTBP3 in human tumours." (PMID 35359851, 2022). "We also explored PTBP3 genetic alterations in different tumour tissues." (PMID 35359851, 2022). "IHC showed that PTBP3 knockdown significantly decreased Ki67 expression in xenograft tumor." (PMID 35016691, 2022). "This study showed that PTBP3 is highly expressed in most tumours." (PMID 35359851, 2022). "Our result our results showed that PTBP3 knockdown decreased tumor cell growth in vitro and vivo." (PMID 35016691, 2022). "Given that the expression of PTBP3 in KIRC tumor tissues was significantly lower than that in control tissues, PTBP3 may be a tumor suppressor molecule in KIRC." (PMID 36203873, 2022). "Moreover, cell counting kit 8 (CCK-8) assays, colony formation assays and in vivo tumor formation assays were used to examine the effects of PTBP3 on LUSC cell proliferation." (PMID 35016691, 2022). "PTBP3 was highly expressed in most tumours, and predicts poor survival." (PMID 35359851, 2022). "In general, we found that the expression of PTBP3 is elevated in most human tumours." (PMID 35359851, 2022). "Thus, the TIMER, CIBERSORT, CIBERSORT-ABS, TIDE, XCELL, MCPCOUNTER, QUANTISEQ, and EPIC algorithms were used to analyse the relationship between PTBP3 expression and tumour-infiltrating immune cells." (PMID 35359851, 2022). "In addition, the mRNA and protein level of PTBP3 was overexpression in our own clinical tumor tissues compared to normal tissues." (PMID 35016691, 2022). "The growth of tumor xenografts was inhibited when PTBP3 gene was silenced." (PMID 32974175, 2020). "PTBP3 was able to promote tumour cell growth in vitro and in a xenograft mouse model in vivo." (PMID 31989778, 2020). "Moreover, PTBP3 promoted tumor cell proliferation, migration and invasion in vitro and tumor growth and metastasis in vivo." (PMID 31291975, 2019). "In addition, we have demonstrated that PTBP3 promoted tumor growth and metastasis via enhancing the translation of HIF-1α, as proven by a series of in vitro and in vivo experiments." (PMID 31291975, 2019). "Interestingly, the weight of tumours formed by PTBP3 knockdown was lower than that of control cell lines, suggesting that PTBP3 knockdown inhibited tumourigenesis in vivo, at least in this model." (PMID 29752441, 2018). "In addition, tumours from PTBP3-knockdown mice exhibited higher CAV1α expression than those from control mice." (PMID 29752441, 2018). "By contrast, few LYVE-1-positive vessel-like structures were observed in PTBP3-knockdown tumours." (PMID 29752441, 2018). "We suggest that the malignant proliferation characteristics of tumour cells in vitro were maintained because the intracellular signal transduction pathway of proliferation was generated by the compensatory mechanism after stable knockdown of PTBP3." (PMID 29752441, 2018). "This might be involved in the effect of PTBP3 on tumour pathogenesis." (PMID 35359851, 2022).
tumor (continued). "Thus, we performed a pan-cancer analysis of the gene expression profile, survival status, genetic alteration, protein phosphorylation, immune infiltration, N6-methyladenosine, and relevant cellular pathways of PTBP3 in various human tumours based on the TCGA, GEO, and CPTAC databases." (PMID 35359851, 2022). "Furthermore, we found a significant correlation between PTBP3 expression and tumour mutational burden and microsatellite instability in various human tumours, and found that PTBP3 expression was positively correlated with TMB in ACC, STAD, PAAD, LUAD, and SARC." (PMID 35359851, 2022). "Therefore, we explored PTBP3 genetic alterations in different tumour tissues." (PMID 35359851, 2022). "Thus, we compared PTBP3 phosphorylation levels between normal and tumour tissues." (PMID 35359851, 2022). "However, in the in vivo environment, stable knockdown of PTBP3 may inhibit tumour differentiation and growth by affecting the tumour microenvironment and not only through the CAV1 pathway." (PMID 29752441, 2018). "In addition, when a mouse xenotransplant model of MKN45 was established, knockdown of PTBP3 in MKN45 cells caused the formation of tumours that were smaller in size than their counterparts, with suppression of tumour lymphangiogenesis and metastasis to regional lymph nodes." (PMID 29752441, 2018). "The results of our study show that PTBP3 expression is increased in a tumour cell line selected for lymphatic metastasis and provides direct evidence supporting the hypothesis that the inhibition of PTBP3 can block tumour lymphangiogenesis and suppress lymph node metastasis." (PMID 29752441, 2018). "Through lentiviral transfection, we achieved PTBP3 overexpression in these modified cells, allowing us to assess the impact of PTBP3 on COX11 splicing events and their implications for tumor biology." (PMID 40270362, 2025). "We performed a 3D matrix gel tumor spheroid assay using the established MKN45 and SNU‐1 cell lines to assess the impact of PTBP3 overexpression or knockout on spheroid invasive growth, quantifying spheroid diameters." (PMID 40270362, 2025). "To explore the involvement of PTBP3 in modulating the alternative splicing of COX11 in vivo, we constructed MKN45 cells expressing luciferase, enabling the monitoring of changes in tumor behavior." (PMID 40270362, 2025). "Using a HuPBMC mouse model, the role of PTBP3 and ΔIL‐18 in promoting GBC growth is confirmed, and showed that an antisense oligonucleotide that blocked ΔIL‐18 production displayed anti‐tumor activity." (PMID 39116343, 2024). "The staining results showed that except for the PTBP3 protein in the EOC tissue of patient #22, PTBP3 protein in the EOC group had obvious staining in the remaining 18 pairs, and this finding confirmed the high expression of PTBP3 in EOC tumor tissues." (PMID 36717926, 2023). "We first investigated the PTBP3 expression in LUAD and LUSC, both of which were significantly increased in tumor tissues compare to normal tissues base on TCGA dataset." (PMID 35016691, 2022). "Knockdown PTBP3 expression inhibited LUSC cell proliferation in cultured cell lines and decreased tumor growth in animal model." (PMID 35016691, 2022). "Therefore, these current findings imply that PTBP3 may be a new and promising tumour biomarker." (PMID 35359851, 2022). "However, the oncogenic role of PTBP3 in various human tumours remains unclear." (PMID 35359851, 2022). "The results showed that in most tumor types, the expression levels of PTBP1 and PTBP3 in tumor tissues were significantly higher than that in non-tumor tissues." (PMID 36203873, 2022). "After excluding general RNA-binding proteins, four potential tumor progression-related proteins (TAF15, HNRPK, NKRF and PTBP3) were identified." (PMID 32393270, 2020). "We analysed the expression levels of PTBP3 using tissue microarray containing 568 CRC tissues and corresponding non-tumor adjacent tissues." (PMID 31291975, 2019).
tumor (continued). "Data showed that blocking the HIF-1α pathway by 2-MeOE2 dramatically reduced tumor volume and weight formed by HCT116 PTBP3 OE cells, highlighting HIF-1α as a critical effector of PTBP3-mediated malignant features." (PMID 31291975, 2019). "In the current study, we showed that reduced PTBP3 expression inhibited the motility of MKN45 cells in vitro and suppressed tumour lymphangiogenesis and metastasis to regional lymph nodes in vivo." (PMID 29752441, 2018). "Similarly, in SNU‐1 cells with PTBP3 knockout, silencing of S‐COX11 expression further inhibited tumor spheroid invasion." (PMID 40270362, 2025). "Notably, miR-181b-5p and miR-877-5p acted as negative regulators of tumor-suppressor genes (e.g., HEY2, MCL2, HAND2), while miR-204-5p and miR-143-3p appeared to indirectly target oncogenes (e.g., RAB10, DR1, PTBP3, NCBP1)." (PMID 41009685, 2025). "In the training cohort, TMA slides containing 74 cases of RCC tissues with paired non-tumor tissues, we observed significantly higher PTBP3 expression in tumor tissues than in paired adjacent non-tumor tissues." (PMID 38405614, 2024). "We finally identified PTBP1 in ACC, KIRP, and LGG; PTBP2 in ACC and KICH; and PTBP3 in ACC, LGG, and PAAD as potential prognostic biomarkers that may be involved in tumor progression in these tumor types." (PMID 36203873, 2022). "Mature miR-612 is a tumor-suppressive gene generated by alternative splicing, and the balance between the two NEAT1 transcripts and miR-612 can be regulated by polypyrimidine tract binding protein 3 (PTBP3)." (PMID 36011001, 2022). "However, further investigation was still needed to elucidate the PTBP3 mechanism for the progression of LUSC, which will help to better understanding tumor progression of LUSC and guide the development of therapeutic targets for LUSC." (PMID 35016691, 2022). "Stable knockdown of PTBP3 does not affect proliferation in vitro but does inhibit tumour growth in vivo." (PMID 29752441, 2018). "Mechanistically, through full‐length transcriptome sequencing, PTBP3 mediates exon 4 skipping in its target gene COX11, leading to shorter transcripts that impair COX11 protein function, reducing mitochondrial copper content and enabling tumor cells to evade cuproptosis." (PMID 40270362, 2025). "We first transfected si-PTBP3 and a negative control(si-NC) into HepG2 cells to determine whether decreased PTBP3 could inhibit the proliferation, migration and invasion of tumour cells." (PMID 37633911, 2023). "However, the correlations between PTBP3 expression and gender (P = 0.671), age (P = 0.884), smoking status (P = 0.217), tumor size (P = 0.292) and tumor classification (P = 0.082) were not statistically significant." (PMID 32477006, 2020). "In 27 of 33 tumours, the expression of PTBP3 was positively correlated with the expression of immune checkpoints PDCD1LG2, while a negative correlation was found in the tumour of THYM." (PMID 35359851, 2022). "In addition, the expression of PTBP3 was positively correlated with the expression of immune checkpoints PDCD1LG2 in most tumours, while a negative correlation was only found in THYM tumours." (PMID 35359851, 2022).